KBTBD6 (kelch repeat and BTB domain containing 6)
Description:
As part of the CUL3(KBTBD6/7) E3 ubiquitin ligase complex functions as a substrate adapter for the RAC1 guanine exchange factor (GEF) TIAM1, mediating its 'Lys-48' ubiquitination and proteasomal degradation. By controlling this ubiquitination, regulates RAC1 signal transduction and downstream biological processes including the organization of the cytoskeleton, cell migration and cell proliferation. Ubiquitination of TIAM1 requires the membrane-associated protein GABARAP which may restrict locally the activity of the complex.
Synonyms: DKFZp547E1912
Tractability: Small molecule: it belongs to a druggable protein family. PROTAC: ubiquitination databases record sites on it.
Gene: Protein-coding gene on chromosome 13 (41,127,569 to 41,132,802, reverse strand). Ensembl gene ENSG00000165572.
Subcellular location: Cytoplasm; Nucleus
Pathways (Reactome):
Immune System: Antigen processing: Ubiquitination & Proteasome degradation
Metabolism of proteins: Neddylation
Gene Ontology:
Molecular function: protein binding; ubiquitin-like ligase-substrate adaptor activity
Biological process: proteasome-mediated ubiquitin-dependent protein catabolic process; protein K48-linked ubiquitination; regulation of Rac protein signal transduction; protein ubiquitination
Cellular component: Cul3-RING ubiquitin ligase complex; cytoplasm; nucleus; cytosol
Genetic constraint (gnomAD): Loss-of-function variants: 8 observed, 42.35 expected, observed/expected ratio (o/e) 0.19, 90% interval 0.11 to 0.34. The upper end of that interval is the gene's LOEUF score, 0.34, which puts it in group 1 of 6, group 1 being the genes least tolerant of losing a copy. Missense variants: 555 observed, 883.7 expected, observed/expected ratio (o/e) 0.63, 90% interval 0.58 to 0.67. Synonymous variants: 285 observed, 340.37 expected, observed/expected ratio (o/e) 0.84, 90% interval 0.76 to 0.92.
Homologues: Orthologues: chimpanzee KBTBD6 (99% identical), pig KBTBD6 (92% identical), dog KBTBD6 (91% identical), mouse Kbtbd6 (57% identical). Paralogues in human: KBTBD7 (89% identical), KLHL21 (23% identical), KLHL20 (22% identical), KBTBD8 (22% identical), KLHL3 (22% identical), KLHL17 (22% identical), KLHL2 (22% identical), KLHL6 (22% identical), KLHL24 (21% identical), KLHL4 (21% identical), KLHL9 (21% identical), KLHL13 (21% identical), and 42 more.
Diseases named in the same sentence as KBTBD6 in open-access papers:
KBTBD6 is named in the same sentence as 2 diseases in open-access papers, as found by Europe PMC text mining. Sharing a sentence is not in itself a finding about the gene and the disease.
KBTBD6 shares sentences with these, for which no sentence is quoted: cancer (1 paper); retinoblastoma (1).